TRDC (T cell receptor delta constant)
Description:
Constant region of T cell receptor (TR) delta chain that participates in the antigen recognition. Gamma-delta TRs recognize a variety of self and foreign non-peptide antigens frequently expressed at the epithelial boundaries between the host and external environment, including endogenous lipids presented by MH-like protein CD1D and phosphoantigens presented by butyrophilin-like molecule BTN3A1. Upon antigen recognition induces rapid, innate-like immune responses involved in pathogen clearance and tissue repair. Binding of gamma-delta TR complex to antigen triggers phosphorylation of immunoreceptor tyrosine-based activation motifs (ITAMs) in the CD3 chains by the LCK and FYN kinases, allowing the recruitment, phosphorylation, and activation of ZAP70 that facilitates phosphorylation of the scaffolding proteins LCP2 and LAT. This lead to the formation of a supramolecular signalosome that recruits the phospholipase PLCG1, resulting in calcium mobilization and ERK activation, ultimately leading to T cell expansion and differentiation into effector cells. Gamma-delta TRs are produced through somatic rearrangement of a limited repertoire of variable (V), diversity (D), and joining (J) genes. The potential diversity of gamma-delta TRs is conferred by the unique ability to rearrange (D) genes in tandem and to utilize all three reading frames. The combinatorial diversity is considerably increased by the sequence exonuclease trimming and random nucleotide (N) region additions which occur during the V-(D)-J rearrangements.
Gene: T-cell receptor constant (C) gene on chromosome 14 (22,462,932 to 22,465,787, forward strand). Ensembl gene ENSG00000211829.
Subcellular location: Cell membrane
Homologues: Orthologues: mouse Trdc (72% identical), guinea pig TRDC (64% identical), dog TRDC (64% identical). Paralogues in human: IGHM (20% identical), IGHA2 (18% identical), IGHA1 (18% identical), IGHG1 (16% identical), IGHG3 (16% identical), IGHG2 (15% identical), IGHD (14% identical), IGHG4 (14% identical), IGHE (14% identical), IGHV5-10-1 (7% identical), IGHV3-53 (6% identical), IGHV3-64D (6% identical), and 65 more.
Diseases named in the same sentence as TRDC in open-access papers:
TRDC is named in the same sentence as 8 diseases in open-access papers, as found by Europe PMC text mining. Sharing a sentence is not in itself a finding about the gene and the disease. The quoted sentences say what the papers report.
brain tumors (1 paper, 2022). "Interestingly, these analyses did not only evidence increased levels of TGF-β1 transcripts (TGFB1) in GBM, they also showed the elevated presence of Vδ TCR chain transcripts (TRDC) in these brain tumors." (PMID 36741364, 2022).
COVID-19 (1 paper, 2022). A disease caused by infection with severe acute respiratory syndrome coronavirus 2. "In line with our finding that the expression of TRDC decreased in the blood of COVID-19 patients, previous studies have suggested decreased proportions of gamma-delta T cells in the blood of hospitalized COVID-19 patients compared to healthy controls." (PMID 35991542, 2022).
infection (1 paper, 2022). The state of being infected such as from the introduction of a foreign agent such as serum, vaccine, antigenic substance or organism. "The CeD-dominated cluster C1 differentially expressed genes including TRGC2, IKZF2, GPR18, TRDC and KLHL42 that are associated with ‘infection’ related response pathways including ‘NOD-like receptor signaling pathway’ in gene ontology analysis." (PMID 35995787, 2022).
TRDC also shares sentences with these, for which no sentence is quoted: cancer (1 paper); colorectal cancer (1); kidney cancer (1); neurological disorder (1); tumours (1).